ZEB2 (zinc finger E-box binding homeobox 2)
Diseases named in the same sentence as ZEB2 in open-access papers (continued):
Sharing a sentence is not in itself a finding about the gene and the disease.
oral cancer (7 papers, 2013 to 2025). "Taking into consideration all these limitations, population-based mutation and expression profiling will provide concrete evidence of the possible association of ZEB2 with oral cancer." (PMID 37927751, 2023). "Elevated expression of Zeb1 in mouse oral cancer cells increases the endogenous levels of Zeb2, and conversely, heightened Zeb2 expression similarly upregulates Zeb1." (PMID 40703656, 2025). "Here, we separately overexpressed ZEB1 and ZEB2 in C57BL/6 mouse oral cancer (MOC) cells and investigated their cellular characteristics, including E‐cadherin levels, motile properties, chemoresistance, and metastatic ability in immunocompetent mice." (PMID 39362647, 2024). "Overall, these results indicated that ZEB2, presumably through its involvement in EMT and cell migration/invasion, contributed to the initiation and spread of oral cancer." (PMID 37927751, 2023). "miR-200 family members directly bind to ZEB1 and ZEB2 mRNAs in many types of cancers, including oral cancer, and induce EMT by decreasing ZEB1 and ZEB2 expression." (PMID 35204785, 2022). "Notably, both expressions of TWIST1 and ZEB2 have been reported to be of significant prognostic value in early stage colorectal and oral cancer patients where disease spread is not always evident." (PMID 26214683, 2015). "Although the mechanism for p120-catenin down-regulation in carcinoma tissues is not defined clearly, it is transcriptionally inactivated by ZEB2, an E-cadherin repressor that is predominantly expressed at the invasive front of oral carcinomas with worse prognosis." (PMID 23936352, 2013).
pulmonary fibrosis (7 papers, 2016 to 2025). Chronic progressive interstitial lung disorder characterized by the replacement of the lung tissue by connective tissue, leading to progressive dyspnea, respiratory failure, or right heart failure. "As expected, as P. agglomerans antigen-induced pulmonary fibrosis progressed, expression of Snail2, Zeb1, and Zeb2 increased in both VD3-sufficient and VD3-deficient mice, but their levels were significantly higher in animals on the restricted diet." (PMID 41465203, 2025). "The pro-inflammatory factor TWEAK can enhance the EMT of human bronchial epithelial cells induced by TGF-β by activating the p38 MAPK/ZEB2 pathway, causing airway inflammation and remodeling, and promoting pulmonary fibrosis." (PMID 36544104, 2022). "In addition, ZEB2 would be a novel therapeutic target for pathogenic diseases involving fibrosis, including liver cirrhosis, cardiac fibrosis, pulmonary fibrosis and scleroderma." (PMID 28422173, 2017). "We next addressed how the expression of EMT-inducing transcription factors, Snai1, Snai2, Twist1, Twist2, Zeb1 and Zeb2, changed in the lungs from WT and Plaur-/- mice at Day 7, 14, 21 and 28 after bleomycin-induced pulmonary fibrosis." (PMID 36674896, 2023). "In lung epithelial cells, TM4SF5 expression leads to suppression of ZEB2, which in turn increases alternative splicing factors for CD44 isoforms (from the standard CD44 form to CD44v8-10 variant form) during idiopathic pulmonary fibrosis." (PMID 34921636, 2021). "The expression of ZEB2 was increased in radiation-induced pulmonary fibrosis have been identified in previous reports, which suggested a possible function of ZEB2 in modulating fibrosis diseases." (PMID 29375381, 2017). "Therefore, it seems that enhanced expression of ZEB2 is an indispensable part of the mechanism by which uc.77 promotes EMT during lung fibrosis." (PMID 26824344, 2016).
renal fibrosis (7 papers, 2016 to 2025). A final common manifestation of a wide variety of chronic kidney diseases characterized by glomerulosclerosis and tubulointerstitial fibrosis. "We have previously shown that loss of ZEB2 in nephron progenitors leads to glomerulocystic kidney disease without renal fibrosis." (PMID 36445780, 2023). "Furthermore, in the UUO mice model of renal fibrosis, Sch B markedly decreases the expression of collagen IV and vimentin in the kidney, and the levels of pro-fibrotic transcription factors, including Slug and Zeb2, are also reduced." (PMID 38067580, 2023). "Therefore, it is plausible that Zeb2 may ultimately regulate upstream of SMAD which would explain why when inhibited in Zeb2 cKO mice there is differentiation of Foxd1-positive pericytes into myofibroblasts, ultimately contributing to the progression of renal fibrosis." (PMID 38808357, 2024). "LncRNA MALAT1 sequesters miR-145 and induces the expression of the transcription factor zinc finger E-box binding homeobox 2 (ZEB2) expression, which promotes the transcription of ECM genes aiding renal fibrosis." (PMID 36010595, 2022). "The zinc finger E-box binding homeobox-1 (Zeb1) and Zeb2 are two transcription factors located downstream of TGF-β1 signaling pathway which can repress E-cadherin and regulate renal fibrosis." (PMID 26881255, 2016). "In our previous study, we found that metanephric mesenchyme-specific Zeb2-cKO (Zeb2fl/fl;Six2-Cre+) mice develop glomerulocystic disease without renal fibrosis." (PMID 36445780, 2023).
schizophrenia (7 papers, 2020 to 2025). A major psychotic disorder characterized by abnormalities in the perception or expression of reality. "Three statistical significant variants are located in intronic regions of ZEB2 (lowest p-value 1.828 × 10− 10), a gene which has been identified to be a risk locus for schizophrenia and to be inducible by nicotine." (PMID 33004014, 2020). "There are indirect protein-protein interactions between proteins encoded by ZEB2 and QPCT genes, and the related pathways also appear to be prominent in the genetic etiology of schizophrenia." (PMID 34867169, 2021). "Taken together, the link between ZEB2 and neurological development and phenotypes makes ZEB2 a plausible candidate gene for schizophrenia." (PMID 31616042, 2020). "Furthermore, in previous studies, we identified putative enhancer RNAs that target schizophrenia-associated genes as well as numerous genetic variants in genes that have been previously linked to schizophrenia, namely GABRB2, SPATS2L, ZEB2, and KCHN8." (PMID 34954808, 2022). "Thus, it could be suggested that ZEB2 is a contributing factor affecting GABAergic cortical interneurons for the subsequent development of schizophrenia." (PMID 34199024, 2021). "C2H2 type subfamily plays an important role in schizophrenia including ZNF521 and ZEB2." (PMID 34867169, 2021). "Among them SPATS2L, ZEB2, and KCHN8, all of which have been identified in schizophrenia studies." (PMID 33004014, 2020).
Stroke (7 papers, 2009 to 2024). Sudden impairment of blood flow to a part of the brain due to occlusion or rupture of an artery to the brain. "Exosomes delivering Zeb2/Axin2 have been shown to enhance post-stroke neuroplasticity, increase neurogenesis, and boost the concentration of BDNF." (PMID 39095888, 2024). "Hsa-miR-142-3p was significantly downregulated in various stroke subtypes, consistent with our data, and expression of its target ZEB2 has been reported to be significantly increased following ischemic stroke." (PMID 35328807, 2022). "Overall our results establish that TRPC6 is a novel target of HIF1α/ZEB2 axis and that transduces stroke-induced ischemia-hypoxia injury in podocytes." (PMID 31784544, 2019). "Furthermore, increasing evidence suggests Zeb2/Axin2’s role in neurogenesis contributes to post-stroke functional recovery." (PMID 39095888, 2024). "Interestingly, in stroke-induced rats, we observed elevated expression of ZEB2 along with HIF1α in the glomerular podocytes." (PMID 31784544, 2019). "Immunostaining data revealed that increased expression of HIF1α, ZEB2, and TRPC6 in glomeruli from stroke-induced rats." (PMID 31784544, 2019).
viral infection (7 papers, 2016 to 2024). "Further unbiased investigation into the most expressed genes per cluster revealed a plethora of genes previously reported in the context of viral infections, such as Il7r, Tcf7, Zeb2, Klrg1, Gzma, Gzmb, Gzmk, Vim, Lgals3, Tox, Lag3, Pdc1, Id3." (PMID 35185882, 2022). "It has been reported that Zeb2 is required for programming CD8+ T cells for terminal differentiation in response to viral infection." (PMID 32226549, 2020). "As GATA3 has been implicated in CD8 T cell function, it is possible that a Zeb2/G9a/GATA3 complex is critical for the function of CD8 T cell function during viral infection." (PMID 28443098, 2017). "The upregulation of Zeb2 is dependent upon the TF T-bet (Tbx21) and expression of Zeb2 is critical for the terminal differentiation of effector CD8 T cells that are required for immunity to viral infection." (PMID 28443098, 2017). "Moreover, although Zeb2 is also critical for short-lived effector cell (SLEC) function in acute viral infection, Zeb2 activity was predicted to occur at intermediate levels in recently activated, progenitor, and effector CD8 T cells in the islets." (PMID 35667687, 2022). "Compared to cluster 4, cluster 2 cells showed higher expression of SLAMF7, ZEB2, GZMB, GPR18, CD72, PDCD1 (PD1) and CRTAM that are known to be expressed in terminally differentiated effector cells in viral infections and various cancers." (PMID 38501302, 2024). "Interestingly, DoRothEA analysis predicted that the TF Zeb2, known to promote the function of long-lived effector cells (LLECs) and effector memory CD8 T cells in acute viral infection, is active in splenic effector memory, AY036118+, and Cx3cr1+ effector cells." (PMID 35667687, 2022).
coronary artery disease (6 papers, 2021 to 2024). "From human genetics, ZEB2, a master regulator of EndMT, was found to be a coronary artery disease associated gene, and ZEB2 regulates SMC phenotypic transition through epigenetic inhibition of TGFβ and NOTCH signaling in atherosclerosis." (PMID 38031118, 2023). "ZEB2 and PLCG2 genes have shown stronger associations with coronary artery disease, with an association value>0.3." (PMID 35844366, 2022). "Although follow-up studies will have to provide more detailed insights into the exact mechanisms, both the identification of ZEB2 and its downstream signals offer potential new therapeutic opportunities for patients suffering from ischemic heart disease." (PMID 33398012, 2021). "Huang found that Yangxin Tongmai Formula affected methylation of zinc finger E-box-binding homeobox 2 (ZEB2) in coronary heart disease with blood stasis syndrome." (PMID 34257689, 2021). "Also, in patients suffering from ischemic heart disease, ZEB2 expression could be confirmed in a portion of cardiomyocytes, while we were unable to detect a signal in the control human heart." (PMID 33398012, 2021). "This positive correlation between the expression of ZEB2 and the TMSB2 and PTMA could also be confirmed in cardiac samples from patients suffering from ischemic heart disease, suggesting a conserved mechanism." (PMID 33398012, 2021).
diabetes (6 papers, 2008 to 2024). "The DM VitDD group presented an increase of ZEB2 protein expression at 24 weeks after diabetes induction compared to Ctrl VitDD and DM VitD groups (P = 0.003)." (PMID 37391399, 2023). "Nephroseq analysis revealed increased expression of HIF1α, ZEB2, and TRPC6 in Nakagawa CKD dataset and Hodgin Diabetes Mouse Glomeruli datasets." (PMID 31784544, 2019).
diabetic nephropathy (6 papers, 2019 to 2025). "For instance, exosomal miR-215-5p derived from ADSCs alleviates epithelial-mesenchymal transition of podocytes in diabetic nephropathy by suppressing zinc finger E-box binding homeobox 2 (ZEB2)." (PMID 40640922, 2025). "A recent published study suggests that the CML induces epithelial mesenchymal transformation in renal podocytes via transcription factor Zeb2, implicating its role in diabetic nephropathy." (PMID 37958795, 2023).
Ewing sarcoma (6 papers, 2015 to 2023). A small round cell tumor that lacks morphologic, immunohistochemical, and electron microscopic evidence of neuroectodermal differentiation. "ZEB2 positively regulates mesenchymal genes and migration and negatively regulates expression of epithelial genes in Ewing sarcoma cells." (PMID 36505823, 2022). "Another critical TF highly expressed by Ewing sarcoma cells is ZEB2, which can induce expression of epithelial-mesenchymal transition (EMT) genes during normal development and in some cancers." (PMID 36505823, 2022). "EWS/FLI and NKX2.2 repressed genes activated by ZEB2, which was shown to block Ewing sarcoma epithelialization." (PMID 32626526, 2020). "These are in stark contrast to the EWS/FLI-depleted phenotype and strongly suggested that ZEB2 repressed epithelial features of Ewing sarcoma." (PMID 26000096, 2015). "We therefore propose that EWS/FLI, through upregulation of NKX2-2, and ZEB2 act to repress differentiation in opposite directions along the epithelial-mesenchymal spectrum; together, they maintain Ewing sarcoma cells in a partially differentiated state." (PMID 26000096, 2015). "Knockdown of ZEB2 in Ewing sarcoma cells induced morphological changes, such as a pronounced actin ring around the cell periphery, a cobblestone cell shape, and hampered cell migration in a scratch assay." (PMID 26000096, 2015). "Strikingly, we found that EWS/FLI-and NKX22-repressed genes are activated by ZEB2, which was previously shown to block Ewing sarcoma epithelialization." (PMID 26000096, 2015). "Recently, we showed that the transcription factor and mesenchymal differentiation gene ZEB2 was highly expressed in both mesenchymal stem cells and Ewing sarcoma cell lines." (PMID 26000096, 2015). "Thus, the ZEB2 transcriptional profile which represents an “epithelialized” Ewing sarcoma, and the NKX2-2 transcriptional profile which represents a “mesenchymalized” Ewing sarcoma, antagonize each other." (PMID 26000096, 2015).
head and neck cancer (6 papers, 2014 to 2024). A primary or metastatic malignant neoplasm affecting the head and neck. "Contrarily, co-overexpressing Zeb1 and Zeb2 elevated the emigration capability of the head and neck cancer cells." (PMID 32280305, 2020). "Zeb1 and Zeb2 knock-down in the head and neck cancer cells diminished CSC features, including emigration, self-renovation capacities, and stemness markers expressions." (PMID 32280305, 2020). "Knockdown of Zeb1 and Zeb2 in head and neck cancer cells decreased their CSC properties such as self-renewal capacity, the expression of stemness markers, and drug resistance." (PMID 27259269, 2016). "Conversely, co-overexpression of Zeb1 and Zeb2 enhanced sphere-forming ability of head and neck cancer cells." (PMID 27259269, 2016). "Computational analysis was employed to identify the protein network interactions, genetic alterations, gene expression, and the survival analysis of the ZEB2 dysregulated network in the head and neck cancer dataset (HNSCC) from the Cancer Genome Atlas (TCGA), Firehose Legacy." (PMID 37927751, 2023). "Increasing evidence suggested that microRNA mediated E-cadherin expression in the head and neck cancers by directly/indirectly targeting the transcription suppressors of E-cadherin, ZEB1 and ZEB2." (PMID 25161999, 2014).
head and neck squamous cell carcinoma (6 papers, 2020 to 2025). A squamous cell carcinoma that arises from any of the following anatomic sites: lip and oral cavity, nasal cavity, paranasal sinuses, pharynx, larynx, and salivary glands. "Analysis of The Cancer Genome Atlas (TCGA) dataset showed that ZEB2 is substantially elevated in head and neck squamous cell carcinoma (HNSC), and microarray data from the GSE12452 dataset indicated similarly elevated expression in NPC tissues." (PMID 41194937, 2025). "ETS1 is required for ZEB2-induced EMT phenotype, where it regulates ZEB2-mediated expression of Twist and MMP-9, and can function as a master regulator of TGF-β-associated EMT in the mesenchymal subtypes of head and neck squamous cell carcinoma (HNSCC)." (PMID 32824207, 2020). "ZEB2 has a highly similar conformation to ZEB1, but its role in head and neck squamous cell carcinoma (HNSCC) cells is not fully understood." (PMID 39362647, 2024). "Firstly, similarly to squamous cell carcinoma of the head and neck, ZEB1 and ZEB2 could be co-expressed and regulated together." (PMID 35565409, 2022).
oral squamous cell carcinoma (6 papers, 2015 to 2024). "In addition, co-expression of TWIST1 and ZEB2 was observed in patients with oral squamous cell carcinoma and was significantly associated with poor survival." (PMID 35884488, 2022). "The expression of ZEB2 was shown to be considerably higher in oral squamous cell carcinoma (OSCC) tissues compared to healthy oral tissues." (PMID 37927751, 2023). "The co-expression of ZEB2 and TWIST1 has been previously reported in patients with oral squamous cell carcinoma." (PMID 35884488, 2022). "Previous laser capture microdissection studies in both CRC and oral squamous cell carcinomas show that tumor buds over-express EMT-related genes such as ZEB1, ZEB2, DES, TGFB3, and VIM in comparison to the main tumor mass." (PMID 31316988, 2019). "However, it remains unclear whether there is a direct link between ZEB2 and TWIST1 in oral squamous cell carcinoma and other carcinomas." (PMID 35884488, 2022).
small cell lung carcinoma (6 papers, 2017 to 2022). Small cell lung cancer (SCLC) is a highly aggressive malignant neoplasm, accounting for 10-15% of lung cancer cases, characterized byrapid growth, and early metastasis. "Moreover, also in small cell lung cancer, miR-200b reduces drug resistance namely by modulating ZEB2, which in small cell lung cancer leads to multidrug resistance of the tumor." (PMID 36158660, 2022). "Correlation between ZEB2 (y-axis) and RAB25 (x-axis) expression from CCLE cell panel datasets analyzed for (a, b) breast (c) colon (d) pancreas, (e) small-cell lung, (f) skin and (g) non-small-cell lung cancer cells." (PMID 30445998, 2018).
triple-negative breast carcinoma (6 papers, 2015 to 2024). An invasive breast carcinoma which is negative for expression of estrogen receptor (ER), progesterone receptor (PR), and human epidermal growth factor receptor 2 (HER2). "In fact, genome-wide profiling of AP-1–regulated transcription has revealed that c-Jun and FosL1 promote cell invasion through the repression of E-cadherin expression by the transcriptional upregulation of ZEB2 in triple-negative breast cancer cells." (PMID 26754630, 2016).
colorectal tumors (5 papers, 2011 to 2023). "According to previous studies, colorectal tumors characterized by high ZEB2, EMT, stem cell traits and low proliferative index are more likely to belong to the CMS4 consensus molecular subtype of CRC." (PMID 35837106, 2022). "In summary, our findings suggest that ZEB2, JAM2, NDN, and PPAP2A, along with the seven transcription factors related to these hub genes, may be associated with the response of colorectal tumors to chemoradiotherapy." (PMID 37636389, 2023). "Furthermore, induction of pri-miR-200a resulted in downregulation of ZEB1, ZEB2, Snail and Slug in colorectal tumor xenografts." (PMID 21929751, 2011).
esophageal cancer (5 papers, 2021 to 2024). A primary or metastatic malignant neoplasm involving the esophagus. "For example, in esophageal cancer, low expression of miR-140-5p can regulate ZEB2 expression to block Wnt/β-catenin signaling, further affecting cancer cell proliferation, invasion, and metastasis." (PMID 39519347, 2024). "Mechanistically, FOXC1 was shown to stimulate EMT in esophageal cancer cells by binding to the Zeb2 promoter directly in a pre-B-cell leukemia homeobox 1 (PBX1)-dependent manner and thereby induce its expression." (PMID 34708244, 2022). "In another study, knockdown of ZEB2 suppressed the migration and invasion of esophageal cancer." (PMID 34551777, 2021).